ENSG00000248235 (novel protein)
Gene: Protein-coding gene on chromosome 8 (22,589,274 to 22,602,084, forward strand). Ensembl gene ENSG00000248235.
Genetic constraint (gnomAD): Loss-of-function variants: 10 observed, 13.45 expected, observed/expected ratio (o/e) 0.74, 90% interval 0.46 to 1.26. Missense variants: 189 observed, 162.36 expected, observed/expected ratio (o/e) 1.16, 90% interval 1.03 to 1.31. Synonymous variants: 81 observed, 67.07 expected, observed/expected ratio (o/e) 1.21, 90% interval 1.01 to 1.45.